ALB (albumin)
Diseases named in the same sentence as ALB in open-access papers (continued):
Sharing a sentence is not in itself a finding about the gene and the disease.
renal failure (continued). "Of the risk factor for recurrent FSGS, including kidney failure within 3 years of onset, mesangial hypercellularity on initial biopsy, young age at presentation, nephrectomy status, white race, low serum albumin level, and living donor transplantation, this patient had few risk factors." (PMID 38580974, 2024). "In fact, hyperfiltration seems to be sustained by increased blood pressure, glucose load and metabolic dysfunction and it may enhance albumin ultrafiltration and excretion, thus causing renal stress and ultimately leading to kidney failure." (PMID 37958820, 2023). "In addition, our work suggested that serum albumin and oliguria/anuria were considered the prominent interactive factors that affect the relationship between C3 and the risk of kidney failure by the interaction analysis." (PMID 35874697, 2022). "A multicenter group have evaluated the four-variable (age, sex, eGFR and urine albumin-to-creatinine ratio) kidney failure risk equation in KT recipients, and concluded that the equation accurately predicts graft failure, especially in patients with eGFR < 45 mL/min/1.73 m2." (PMID 36294429, 2022). "In the literature, there are data (observed in patients with severe kidney failure) suggesting that vitamin D deficiency might play a role in the impairment of albumin synthesis." (PMID 32471106, 2020). "A useful aid in predicting the likely timing of the onset of ESKD is the Kidney Failure Risk Equation, which uses the age, sex, estimated glomerular filtration rate (eGFR), urine albumin/creatinine, calcium, phosphate, bicarbonate and albumin to predict the risk of progression to ESKD over 5 years." (PMID 29582148, 2019). "The outcomes included kidney failure events, the rate of change in estimated glomerular filtration rate (eGFR) per year, all cause death events, and changes in proteinuria, serum phosphorus concentration, serum albumin, and body mass index (BMI)." (PMID 30403710, 2018). "It seems that the interaction between various degrees of renal insufficiency and albumin loss could be important on ApN levels." (PMID 26089882, 2015). "Hyperfiltration might enhance albumin ultrafiltration and excretion, and eventually shift to a phase of progressive loss of renal function, which, paralleled to a further rise in albuminuria, ultimately leads to kidney failure." (PMID 33923418, 2021). "The results of present study also demonstrated low serum albumin levels in diabetic control group which may be a case due to renal insufficiency leading to loss of proteins, and/or due to metabolic disturbance resulting in increased protein catabolism or insulin deficiency." (PMID 29270392, 2017). "The kidney failure risk equation (KFRE) estimates the risk of progression to kidney failure (KF) on age, sex, estimated glomerular filtration rate (eGFR) and urine albumin-to-creatinine ratio." (PMID 42152438, 2026). "This study compared 50 children with kidney failure on hemodialysis and 50 healthy age-matched controls, assessing growth and nutrition through anthropometric and serum measures (albumin, uric acid, cholesterol) after six months of dietary management." (PMID 41073614, 2026). "Another prediction tool called Index4 is calculated based on only four parameters, including the Eastern Co-operative Oncology Group (ECOG) performance status of the patient, low serum albumin, renal insufficiency and the presence of a metastatic cancer." (PMID 40004631, 2025). "Reduced levels of albumin (ALB), an abundant soluble protein component of the circulatory system, are thought to be primarily associated with cachexia, renal insufficiency, hepatic dysfunction, and inflammation." (PMID 40980177, 2025). "The adsorption of UMs to albumin-coated MNPs was evaluated using model solutions of thirty-three UMs at concentrations similar to those observed for patients with kidney failure between HD sessions." (PMID 40508174, 2025).
renal failure (continued). "A retrospective study has shown that albumin as an alternative in cardiopulmonary bypass surgery is safe and effective for patients with increased bleeding or kidney failure." (PMID 39958823, 2025). "Albuminuria is considered a biomarker of kidney damage in patients with CKD, with an increase in urinary albumin excretion identified as a strong predictor of progression to kidney failure." (PMID 41426049, 2025). "The incidence of regular albumin administration and nephrectomy before kidney failure was significantly higher in patients with CNS than in those with infantile NS (P = 0.049 and P = 0.018, respectively)." (PMID 40095038, 2025). "Current clinical scoring systems for predicting the initiation of KRT, such as the kidney failure risk equation (KFRE-2), incorporate the urinary albumin–creatinine ratio and eGFR measured at the index clinic visit." (PMID 40142789, 2025). "Elevated levels of renal inflammatory markers, including urea, creatinine, and decreased albumin, in the disease control clearly indicate renal insufficiency." (PMID 38910883, 2024). "The measurement of blood urea nitrogen and creatinine levels, urine albumin, and the calculation of the creatinine clearance are useful for the evaluation of renal insufficiency and the adjustment of drug dosing." (PMID 39092230, 2024). "The Lille Model measures were age, renal insufficiency, albumin, prothrombin time, bilirubin and day 7 bilirubin levels." (PMID 38650630, 2024). "CKD was calculated using the Modification of Diet in Renal Disease (MDRD) formula based on glomerular filtration rate (GFR)<60 mL/min per 1.73 m2, or albumin/Cr>30 mg/g in random urine, self-reported kidney failure, or dialysis." (PMID 39465521, 2024). "Protein-bound IS and p-cresol are common toxic substances seen in the blood of individuals with kidney failure that are primarily attached to albumin." (PMID 38787079, 2024). "Regarding the criteria for the albumin compensation in the case of an empyema, the most frequent answers found in our study were a low albumin level and the presence of a renal insufficiency." (PMID 37697230, 2023). "Reported high-risk factors of linezolid-induced thrombocytopenia and reduction in the hemoglobin level include low platelet count, low body weight, low level of albumin, old age, longer duration of medication, renal insufficiency, and Cmin >8 mg/L." (PMID 38026932, 2023). "The responders took into account the low albumin level for 18% of them (at the level of 25 g/L) and 20% of the responders took into account the renal insufficiency (at the cut off of 133 μmol/l)." (PMID 37697230, 2023). "Progression of DKD was identified as the transition from one urinary albumin excretion rate (AER) stage to the next or the development of kidney failure during the follow-up period." (PMID 36632821, 2023). "The kidney failure risk equation (KFRE) predicts the 2- and 5-year risk of needing kidney replacement therapy (KRT) using four risk factors — age, sex, urine albumin-to-creatinine ratio (ACR) and creatinine-based estimated glomerular filtration rate (eGFR)." (PMID 37798742, 2023). "Relevant literature have shown that IL6, AKT1, VEGFA, FN1, TIMP1, ALB and TNF are associated with renal insufficiency." (PMID 36209090, 2022). "In this study, the relationship between C3 and kidney failure was further stratified by age, hemoglobin, serum albumin, SCr at presentation, oliguria or anuria, and crescents." (PMID 35874697, 2022). "In addition, we found that serum albumin level was considered the prominent interactive factor that affects the association between C3 and the risk of kidney failure by the interaction analysis, which may be related to complement involvement in the pathogenesis of proteinuria." (PMID 35874697, 2022). "LM is calculated on Day 7 (LM7) of corticotherapy and combines six variables (age, renal insufficiency, albumin, prothrombin time, bilirubin, and evolution of bilirubin at Day 7)." (PMID 34071799, 2021).
renal failure (continued). "Considering that the AUC estimation is cumbersome, Cmin threshold at 48 h and steady state with a value of ≥6.9 mg/L is recommended to improve safety, especially for patients with renal insufficiency and patients with low serum albumin." (PMID 34675806, 2021). "The NZBWF1 mice died of kidney failure, indicated by elevated urinary albumin/creatinine (ALB/CRE) ratios and blood urea nitrogen (BUN)." (PMID 34868046, 2021). "The Kidney Failure Risk Equation (KFRE) is a simple widely validated prediction model using age, sex, estimated glomerular filtration rate, and urinary albumin-creatinine ratio to predict the risk for end-stage kidney disease." (PMID 33319199, 2020). "Excessive urinary albumin measured as the albumin-creatinine ratio (ACR) ≥ 30 mg/g has been shown to be associated with the development of KI and progression of CKD and kidney failure." (PMID 32466510, 2020). "The Kidney Failure Risk Equation (KFRE) employs four variables: age, sex, urine albumin-to-creatinine ratio (ACR), and eGFR in individuals with CKD to predict the risk of ESRD and the need for dialysis or a kidney transplant within 2–5 years." (PMID 33246427, 2020). "Patients in the T group appeared to be more diseased, recognizable by higher APACHE-II scores, lower levels of albumin and hemoglobin, and a larger proportion of cardiac comorbidities and renal insufficiency." (PMID 31852456, 2019). "Patients with renal insufficiency had a lower level of ALB (39.85 ± 5.04 vs 41.97 ± 4.47, p = 0.014)." (PMID 31620002, 2019). "Second, the levels of some antioxidant molecules like albumin and uric acid can change in concomitant conditions such as renal insufficiency and acute phase response." (PMID 30035652, 2018). "The Kidney Failure Risk Equation (KFRE) predicts the need for dialysis or transplantation using age, sex, estimated glomerular filtration rate (eGFR), and urine albumin to creatinine ratio (ACR)." (PMID 29894480, 2018). "Previous studies reported that serum leptin levels were positively correlated with PhA, in hemodialysis patients and with serum albumin in peritoneal dialysis patients." (PMID 30089153, 2018). "Firstly, there are patients with persistent but variable microscopic haematuria, variable renal insufficiency, often renal cysts, and late onset proteinuria with normal albumin/creatinine ratio until eGFR is <60 mL/min." (PMID 28975106, 2017). "Since serum albumin is an important prognosis determinant for chronic dialysis patients, we next performed a multiple regression analysis with serum albumin as the dependent variable among all ESRD patients." (PMID 26998414, 2016). "In conclusion, the present study demonstrates discordant associations of lipid parameters with renal insufficiency and TG/HDL-C is a better marker for evaluating increased urinary albumin excretion and CKD." (PMID 26607500, 2015). "Our results showed that the administration of MCP-1 along with insulin into diabetic mice with moderate kidney failure restored the blood glucose, creatinine, urea nitrogen and urine albumin to physiological levels." (PMID 23451253, 2013). "Patients presented more symptoms of cough with sputum production, and laboratory findings of leukocytosis with left shift, thrombocytopenia, renal insufficiency and lower serum albumin level." (PMID 22393343, 2011). "An only modestly elevated albumin excretion rate—even within the normoalbuminuric range—has been reported to identify risks for incident CKD, kidney failure, cardiovascular disease, and all-cause mortality not only in patients with CKD but also in persons with relatively preserved kidney function." (PMID 41583798, 2026). "Patients with other disorders, on the other hand, had lower vitamin D3 and albumin values, as renal insufficiency and albumin metabolism may be related to impaired oxygen and nutrition supply of this extraordinary old GIH cohort." (PMID 40863037, 2025).
renal failure (continued). "Patients with renal insufficiency tend to have lower plasma albumin concentrations which may result in higher concentrations of unbound melphalan." (PMID 40672810, 2025). "Recipient age, recipient HGB, recipient ALB, donor and recipient BMI, number of HLA mismatches, and primary disease leading to kidney failure have also been found to be predictors of long-term kidney graft survival rate after allograft kidney transplantation in previous studies." (PMID 40236452, 2025). "In our analysis, patients with high albumin levels and lower creatinine had greater β2M DI overall and were not disturbed by initial β2M, which suggested that hypoproteinemia and renal insufficiency could slow the decline of β2M." (PMID 38562177, 2024). "Additionally, there are studies that have reported that serum albumin is a poor nutritional marker in patients with dialysis kidney failure." (PMID 39518586, 2024). "Patients who have known kidney failure may have a worse presentation as the drug may be displaced from albumin by uremic toxins, which can induce intoxication from increased free phenytoin levels." (PMID 39463511, 2024). "Albumin functionality correlates with parameters for inflammation, hepatic, or renal insufficiency." (PMID 37628734, 2023). "The failure of NIPPV treatment leads to the delay of endotracheal intubation time and treatment time, which increases the mortality of patients, which might relate to high CRP concentration, serum albumin, combined renal insufficiency, vomit aspiration." (PMID 37828534, 2023). "Serum albumin after 1 year of PD predicted mortality in peritoneal dialysis." (PMID 35166186, 2022). "Considering that the AUC estimation is cumbersome, the Cmin threshold at 48 h and steady state with a value of ≥6.9 mg/L is recommended in clinical practice to guide dosage adjustment, especially in patients with renal insufficiency and patients with low serum albumin." (PMID 34675806, 2021). "In pregnancy, serum albumin levels may be decreased in cases of renal insufficiency with proteinuria, preeclampsia, gestational hypertension and gestational edema." (PMID 34354103, 2021). "Further, though we did include important and population-specific variables such as age, procedure urgency, kidney failure type, serum sodium and albumin, and several comorbidities, the limited number of outcomes made it statistically inappropriate to adjust estimates for these variables." (PMID 34736410, 2021). "Compared with the HC group, patients on PD had lower levels of total blood proteins (as well as albumin) and iron, and considerably higher levels of urea, creatinine, fibrinogen, and sedimentation rate, as was expected due to kidney failure and systemic inflammation." (PMID 32784866, 2020). "We could also confirm previously published results on oxidized proteins (AOPPs, albumin) and carbonylated proteins, which were significantly elevated in all patient groups and also showed a correlation with the stage of renal insufficiency (oxidized albumin)." (PMID 27698480, 2016). "Although urinary albumin is mainly leaked from blood into urine due to abnormal renal glomerulus and used as a kidney failure marker, ALB mRNA (NCBI Gene ID: 213) in urinary EMV may be originated from epithelial cells throughout nephrons." (PMID 25275511, 2014). "In the absence of intravenous albumin, postparacentesis circulatory dysfunction occurs in approximately 70% of patients and is associated with increased mortality because of hepatorenal syndrome and dilutional hyponatraemia." (PMID 24222902, 2013). "In addition to treatment modality, a comprehensive analysis of age, gender, duration of dialysis, history of renal insufficiency, comorbidities, and baseline levels of Hb, ALB, BNP, PTH, Ca, P, β-CTX, PINP, and BAP showed that only increasing age significantly increased the risk of mortality." (PMID 39713805, 2024).
renal failure (continued). "Notably, persistent DNA damage at telomeres in kidney fibroblasts resulted in kidney failure, as evidenced by an increase in the urinary albumin-to-creatinine ratio (uACR) and a decrease in mouse survival, which coincided with the onset of kidney interstitial fibrosis." (PMID 39349834, 2024). "More patients in the case group had a history of hepatic and renal insufficiency and paraplegia, while patients in the control group had higher mean values of preoperative laboratory indices of platelet count, prothrombin time, activated partial thromboplastin time, total bilirubin, and albumin." (PMID 37781297, 2023). "After adjusting for age, sex, baseline eGFR, hemoglobin, albumin, high-sensitivity C-reactive protein and daily urine output, our results revealed that the high serum DKK1 levels (per 100 pg/mL increase) were associated with an increased risk of kidney failure in the CKD patients." (PMID 37108841, 2023). "The biochemistry analysis in jenny I revealed renal insufficiency highlighted by an increase in both urea (48 mg/dL, RI = 9–31) and creatinine (2.2 mg/dL, RI = 0.59–1.3) as well as a decrease in total proteins (5.6 g/dL, RI = 5.8–7.6) due to a mild reduction in albumin (2.2 g/dL, RI = 2.5–3.2)." (PMID 33240947, 2020). "In our previous study with the peritoneal dialysis (PD) patients, we failed to confirm any significant associations between the amount of urinary excreted Klotho and that of albumin, which is the principal component of urinary protein in cases of glomerular proteinuria." (PMID 23176706, 2012). "In addition, how disease modification can be meaningfully assessed (e.g., the impact of an intervention on mortality and kidney failure, estimated glomerular filtration rate [eGFR], urinary protein or albumin, nonvisible [microscopic] hematuria, and markers of underlying IgAN pathology) is examined." (PMID 41426049, 2025). "Most studies have reported that thrombocytopenia is associated with a high trough concentration of LZD, long course of LZD treatment, combined use of meropenem, low albumin level, low baseline of PLT, and renal insufficiency in the adult population." (PMID 35185555, 2022). "Other predictors of death were WL ≥ 10%, kidney failure, CRP ≥ 2.4 mg/dL, prealbumin <10 mg/dL, albumin <3.00 g/dL and cholinesterase <5064 UI/mL." (PMID 28025528, 2016). "In conclusion, albumin has a dose-dependent effect on survival in patients with ARF and SBP, with the persistence of the dose effect even for patients with renal failure for reasons other than HRS." (PMID 26178624, 2015). "As indicator of renal insufficiency, as compared with LZ rats, ZDF rats had increased renal weights, plasma creatinine, and urine albumin excretion, urinary volume output and sodium excretion." (PMID 26055622, 2015). "The results suggested that when the serum albumin <30 g/L, C3 had a protective effect on outcomes in patients with anti-GBM disease, and serum albumin could modify the relationship between C3 and kidney failure." (PMID 35874697, 2022). "Patient with renal insufficiency showed increased levels of GPC-4 as well as a negative association of GPC-4 levels with GFR and a positive correlation with urinary albumin excretion." (PMID 34903856, 2021). "We found that the patients with glomerular C4c deposition had worse renal insufficiency than those without C4c deposits, along with higher 24-h urinary protein and TG, but lower serum albumin." (PMID 32983156, 2020). "Urine creatinine and albumin concentration were not elevated in UCP1 KO mice, excluding kidney failure as cause for increased water intake, which is in line with previous observations." (PMID 32005798, 2020). "In the intergroup analysis, ALB was lower in patients with renal insufficiency, but showed no significance in the multivariate analysis." (PMID 31620002, 2019).